PRPF38A (pre-mRNA processing factor 38A)
Description:
Involved in pre-mRNA splicing as a component of the spliceosome.
Synonyms: FLJ14936; Prp38; PRP38A
Tractability: Small molecule: a structure with a bound ligand is known. PROTAC: ubiquitination databases record sites on it; its protein half-life has been measured.
Gene: Protein-coding gene on chromosome 1 (52,404,060 to 52,420,836, forward strand). Ensembl gene ENSG00000134748.
Subcellular location: Nucleus
Subcellular location (Human Protein Atlas): Nucleoplasm
Pathways (Reactome):
Metabolism of RNA: mRNA Splicing - Major Pathway
Gene Ontology:
Molecular function: protein binding; RNA binding
Biological process: mRNA splicing, via spliceosome
Cellular component: nucleoplasm; nucleus; precatalytic spliceosome; U2-type precatalytic spliceosome
Genetic constraint (gnomAD): Loss-of-function variants: 7 observed, 32.87 expected, observed/expected ratio (o/e) 0.21, 90% interval 0.12 to 0.4. The upper end of that interval is the gene's LOEUF score, 0.4, which puts it in group 1 of 6, group 1 being the genes least tolerant of losing a copy. Missense variants: 204 observed, 329.71 expected, observed/expected ratio (o/e) 0.62, 90% interval 0.55 to 0.69. Synonymous variants: 102 observed, 112.8 expected, observed/expected ratio (o/e) 0.9, 90% interval 0.77 to 1.07.
Homologues: Orthologues: chimpanzee PRPF38A (100% identical), dog PRPF38A (100% identical), guinea pig PRPF38A (100% identical), macaque PRPF38A (100% identical), pig PRPF38A (100% identical), rabbit PRPF38A (100% identical), mouse Prpf38a (99% identical), rat Prpf38a (92% identical), tropical clawed frog prpf38a (92% identical), zebrafish prpf38a (88% identical), Drosophila melanogaster Prp38 (58% identical), Caenorhabditis elegans prp-38 (51% identical).
Diseases named in the same sentence as PRPF38A in open-access papers:
PRPF38A is named in the same sentence as 5 diseases in open-access papers, as found by Europe PMC text mining. Sharing a sentence is not in itself a finding about the gene and the disease. The quoted sentences say what the papers report.
triple-negative breast carcinoma (2 papers, 2020 to 2021). An invasive breast carcinoma which is negative for expression of estrogen receptor (ER), progesterone receptor (PR), and human epidermal growth factor receptor 2 (HER2). "For example, in an siRNA screen on triple-negative breast cancer cell lines, silencing of PRPF8 and pre-mRNA processing factor 38A (PRPF38A) were shown to confer lethality and disrupt mitosis." (PMID 34065983, 2021). "Moreover, in triple-negative breast cancer cells, the expression of proteasomal genes PSMB4 and PSMB5 was dependent on the expression of splice factors PRPF8 and PRPF38A." (PMID 32545483, 2020).
sarcoma (1 paper, 2021). A usually aggressive malignant neoplasm of the soft tissue or bone. "Among them, high expression levels of SMARCC1, SRSF10, PRPF38A, JARID2, GNAI3, miR-301a-3p, miR-106b-5p, miRNA-130b-3p, miR-423-3p and LINC01296 and low expression levels of ARF3 and PRKCB were associated with shorter overall survival in sarcomas." (PMID 33653335, 2021). "Among the seven survival-associated mRNAs, the high expression levels of SMARCC1, SRSF10, PRPF38A, JARID2 and GNAI3 were significantly associated with shorter overall survival in sarcomas (P = 0.0018, P = 0.037, P = 0.0058, P = 0.0093, and P = 0.0234, respectively)." (PMID 33653335, 2021).
tumor (2 papers, 2013 to 2022). "PHF5A and PRPF38A play an important role in regulating tumour proliferation and migration." (PMID 36434140, 2022). "A set of genes including PRPF38A, RIOK3, QSER1, PSMC3IP, ATAD3B, MGC12982, and C20ORF27 were significantly overexpressed in HCC-R tumor tissue with fold changes ≥4 (P = 0.001 to 0.0001)." (PMID 24377043, 2013).
PRPF38A also shares sentences with these, for which no sentence is quoted: cancer (1 paper); scrapie (1).